HAPSTR2-OT1 (HAPSTR2 overlapping transcript 1)
Synonyms: uc.482
Gene: Long non-coding RNA gene on chromosome X (140,087,667 to 140,159,066, forward strand). Ensembl gene ENSG00000298798.
Diseases named in the same sentence as HAPSTR2-OT1 in open-access papers:
HAPSTR2-OT1 is named in the same sentence as 4 diseases in open-access papers, as found by Europe PMC text mining. Sharing a sentence is not in itself a finding about the gene and the disease.
HAPSTR2-OT1 shares sentences with these, for which no sentence is quoted: hypocalcaemia (1 paper); hypoparathyroidism (1); secondary hyperparathyroidism (1); X-linked hypoparathyroidism (1).